GFAP (glial fibrillary acidic protein)
Diseases named in the same sentence as GFAP in open-access papers (continued):
Sharing a sentence is not in itself a finding about the gene and the disease.
brain tumors (continued). "The intermediate and non-classical monocyte populations, both expressing CD16 (CD16+ monocytes), have a significantly larger fraction of GFAP+ cells in 228 brain tumour patients than in healthy controls (P < 0.001)." (PMID 33501422, 2021). "Similar to the CTC (EpCAM+/CK+) sorting in the blood of lung cancer patients develop brain metastases often reported in the literature, GFAP has a greater advantage in the sorting of brain tumor cells in CSF." (PMID 33208163, 2020). "Nevertheless, IMS shows a correlation between GFAP and the brain tumour markers H2A and Tubulin α-1A, suggesting tumour development." (PMID 32238824, 2020). "The preliminary clinical application of GFAP-IMLs for CTCs separation was verified by thirty-two children with different brain tumors." (PMID 33208163, 2020). "Herein, we for the first time attempted to select GFAP as the main target of positive CTCs sorting, and to investigate its efficiency as a CTCs sorting agent in CSF of brain tumors." (PMID 33208163, 2020). "In this study, for the first time, we introduced the endocytic GFAP antibody of neuroepithelial tumors (NT) as a positive CTCs sorting marker to verify its feasibility in the diagnosis of brain tumors in children." (PMID 33208163, 2020). "In summary, the cytoplasm protein GFAP nanoparticles for magnetic separation prepared in the present study effectively isolated CTCs in CSF and peripheral blood from children with brain tumors." (PMID 33208163, 2020). "This study was to construct CNS neoplasms CTCs separation system based on GFAP antibody immunolipid magnetic liposomes and to verify it in brain tumors." (PMID 33208163, 2020). "Immunohistological analysis of several RAS-Tert brain tumors showed that they were less proliferative and more differentiated, expressing the glial fibrillary acidic protein, GFAP than those that developed in RAS fish." (PMID 32117990, 2020). "NGS method in CTC-DNA detection also indicated that the GFAP targeted CTCs has the features of brain tumors." (PMID 33208163, 2020). "As such, EVs isolated from plasma of brain tumor patients should contain higher concentrations of GFAP and Tau compared to samples from normal patients." (PMID 31311947, 2019). "In contrast, 16/17 (94%) and 11/17 (65%) brain tumor patients had Tau and GFAP rIF above these values, respectively." (PMID 31311947, 2019). "GFAP, expresses almost exclusively in astrocytes, is an essential factor in malignancy progression of brain neoplasms, which serves as a vital component of cytoskeleton." (PMID 31049031, 2019). "A growing number of evidences revealed that GFAP level increased in high-grade brain tumors, implying the important role of GFAP in the aggressiveness of brain tumors." (PMID 31049031, 2019). "Generous studies revealed that epigenetic activation of GFAP or high GFAP expression was correlated with aggressiveness of brain tumor." (PMID 29746255, 2018). "Several studies have suggested that the serum GFAP level is a potential prognostic factor in patients with primary brain tumors." (PMID 28969023, 2017). "GFAP is also highly expressed in astrocytoma such as glioblastomas, the most frequent and devastating type of brain tumors." (PMID 26953813, 2016). "A more selective expression in astrocytes was achieved by an adenovirus that expressed Cre under the control of the GFAP promoter, but this reduced efficacy in eliciting brain tumours." (PMID 26704996, 2016). "Using IHC to identify GBM, we demonstrated that the EGFR (lower-left panel), and the astrocytic marker, GFAP (lower-right panel) were present in brain tumor sections." (PMID 27285755, 2016). "The overexpression of the krasG12V gene driven by cytokeratin 5 (krt5) or glial fibrillary acidic protein promoter induced brain tumor." (PMID 26572230, 2015). "The C6 cells used in this study were initially derived from rat brain tumors and shown to express GFAP, a characteristic marker protein of astrocytes." (PMID 25617894, 2015).
brain tumors (continued). "GFAP, an intermediate fibrous protein, is a marker of astrocyte and a symbol of differentiation into mature cells from brain tumor stem cells." (PMID 26136642, 2015). "During examination of the distribution of the glial fibrillary acidic protein (GFAP) in 131 paraffin-embedded sections of brain neoplasms deriving from either surgical or postmortem specimens, MCs were identified in one case of meningothelial meningioma." (PMID 26377554, 2015). "In this study, we used immunodeficient (i.e., Rag2-/-) transgenic GFAP-luc mice to grow orthotopic brain tumors and to monitor the co-activation of the GFAP promoter with tumor development." (PMID 21247490, 2011). "A recent study revealed robust SOX2 expression in brain tumors of glial lineages expressing the astrocytic marker protein glial fibrillary acidic protein (GFAP)." (PMID 22070920, 2011). "The C6 cell line originated from a chemically induced rat brain tumor and expresses GFAP and vimentin, which is a property of undifferentiated astrocytic cell type." (PMID 22174936, 2011). "For brain tumors, this involves GFAP or Nestin driven expression of the bacteriophage protein Cre, which removes sections of DNA between E. Coli specific DNA sequences known as loxP domains." (PMID 19814820, 2009). "The glial fibrillary acidic protein (GFA) content of 58 human brain tumours was determined by quantitative immunoelectrophoresis, using monospecific antibody against GFA." (PMID 7362772, 1980). "To validate these findings at the protein level, we evaluated FOSL1 expression in glial fibrillary acidic protein (GFAP)‐positive tumor cells—used as a GBM marker—within brain tumor tissues from patients clinically categorized as TMZ resistant or TMZ sensitive." (PMID 41556041, 2026). "Since ALTS1C1 was originally derived from primary astrocytes, to further exclude the possibility that the GFAP signal might come from ALTS1C1, GFAP IF staining on the ALTS1C1-GFP brain tumor section was performed." (PMID 40745073, 2026). "GFAP testing has the potential to streamline the work-up of brain tumors." (PMID 41762323, 2026). "Similarly, the GFAP fragment 388–405, detected in multiple GBM zones, has been associated with pediatric brain tumors." (PMID 40649831, 2025). "GFAP has also been detected in a subset of circulating Mo in brain tumor patients." (PMID 38566128, 2024). "In the context of research to improve radiotherapy of brain tumors, reactive gliosis after irradiation with higher doses (10 Gy) and in systemic context (whole-body X-irradiation of mice) was observed based on upregulation of GFAP in the brain." (PMID 37089489, 2023). "There are three key requirements for elevated serum GFAP levels in brain tumour patients." (PMID 35919979, 2022). "We are always seeking to improve our classification of brain tumours and our results suggest that GFAP may help to differentiate between different tumours and characteristics." (PMID 35919979, 2022). "Also, high levels of histone proteins, haemoglobin subunit α, tubulins, and GFAP were identified in a metastatic brain tumour using IMS-ROI." (PMID 32238824, 2020). "As a first step toward determining whether GFAP and Tau are candidate EV biomarkers for tumor detection, we tested whether these proteins were detectable in EVs isolated from various brain tumor cell lines." (PMID 31311947, 2019). "The analysis of H&E and GFAP sections of NS/CT-2A tumors demonstrated the presence of malignant and highly proliferative brain neoplasms of glial origin neuropathologically behaving like a high-grade anaplastic astrocytoma, probably in transition to a GBM in the light of the high mitotic activity." (PMID 31511246, 2019). "Increasing evidences showed that GFAP level was elevated in high-grade brain tumors, implicating that GFAP might be involved in the aggressiveness of brain tumors." (PMID 29746255, 2018). "It has been proven that GFAP is a pro-tumorigenic factor in brain tumor." (PMID 29746255, 2018).
brain tumors (continued). "Increasing evidences showed that GFAP level elevated in high-grade brain tumors, implicating that GFAP might be involved in the aggressiveness of brain tumors." (PMID 29746255, 2018). "GFAP is very important in malignancy progression of brain neoplasms." (PMID 29746255, 2018). "GFAP is important in malignant progression of brain neoplasm." (PMID 29746255, 2018). "In addition, the patients with high-grade brain tumors tended to have lower serum GFAP than those with low-grade tumors (0.145 ± 0.354 vs. 0.281 ± 0.522 ng/mL; p = 0.097)." (PMID 28969023, 2017). "Remarkably, approximately 5-10% of GFAP positive cells infiltrated the edges of the tumor, suggesting that the activation and infiltration of astrocytes is associated with the growth of IGF-IR positive brain tumors (bottom, arrows)." (PMID 24039934, 2013). "Moreover, the studies of GFAP in brain tumors mainly focus on the predictive value of tumor volume." (PMID 38216970, 2024). "The increased angiogenic character (VEGFhigh) observed in the GFAP-Cre; KrasG12D; APCL/+; p53L/L mice suggests that these pathways contribute to the vascularization of brain tumors, mirroring a key feature of human GBM." (PMID 38473403, 2024). "Orthotopic implantation of BTIC-18 in mice led to a reliable formation of brain tumors that still expressed the proneural progenitor marker SOX-2 (sex determining region Y-box2) and the astrocytic marker GFAP." (PMID 36834608, 2023). "To assess the clinical importance of astrocytic scar barrier in limiting human brain tumor growth, we first validated the presence of astrocytic scar formation in human brain tumor by immunostaining the GBM patient brain tissue with GFAP and CSPGs." (PMID 37468961, 2023). "Further IHC staining of tumor for HGA markers including GFAP, Sox2, nestin, and Ki-67 confirmed the HGA status of the brain tumors." (PMID 35814428, 2022). "Gemistocytes are considered neoplastic GFAP+-p65-Bruton’s tyrosine-kinase+ (BTK+)-expressing astrocytes with a typical cell shape and are found in several brain tumors including GBM." (PMID 35456027, 2022). "Confocal microscopy showed the experimental brain tumor over-expressed the CAV protein and under-expressed the GFAP protein." (PMID 35745855, 2022). "Brain tumor tissue sections were stained for H&E, DAPI (nuclear staining), protein 14-3-3γ (TNT marker), PCNA (proliferation marker), and GFAP (a glial marker) and analyzed by confocal microscopy with subsequent 3D reconstruction." (PMID 34267246, 2021). "IMS-HCA was successful in creating groups consisting of similar signal distribution images of glial fibrillary acidic protein (GFAP) and related multiple proteins in primary brain tumours." (PMID 32238824, 2020). "Our objective is to validate four plasma biomarkers – glial fibrillary acidic protein (GFAP), neurofilament light (NEFL), matrix metalloprotease 3 (MMP3) and fatty acid binding protein 4 (FABP4) – and compare them with established brain tumor molecular markers and survival." (PMID 38879494, 2024). "Vimentin and GFAP citrullination is produced by the PAD2 enzyme, and the identification of citrullinated peptides of these proteins in less aggressive histotypes of pediatric brain tumors would suggest a potential role in clinical prognostic applications." (PMID 37761239, 2023). "In vivo brain imaging of the RG-2 intra-cranial tumors with the CAV PNA or the GFAP PNA antisense radiopharmaceutical demonstrated the under-expression of the GFAP mRNA and the over-expression of CAV mRNA in the intra-cranial brain tumor, providing the PNA was conjugated to the TfRMAb Trojan horse." (PMID 35745855, 2022). "The CD133-positive cells are much less in proportion compared to GFAP-positive cells in tumors formed by AGR53-GSC, DBT-Luc-GSCs, and MGG8-GSCs under FMOD nontargeting conditions, in good correlation to the low proportion of GSCs seen in brain tumors." (PMID 35642785, 2022).
brain tumors (continued). "Prospective studies on GFAP serum levels in brain tumour patients found that GFAP was detected in patients with other non-glial brain tumours." (PMID 35919979, 2022). "Pérez‐Larraya in 2014 published 2-step diagnostic algorithm using glial fibrillary acidic protein (GFAP) and YKL‐40 which differentiated patients with GBM from those with nonglial brain tumours with a sensitivity of 65% and a specificity of 78%26." (PMID 34162919, 2021). "The results indicated that GFAP-IML CTCs isolation system, combined with an EGFR immunofluorescence assay of antitumor marker, can serve as a brand-new method for the identification of CTCs for brain tumors." (PMID 33208163, 2020). "More than 50% of animals in the mutant cohorts GFAP-Cre; PdgfraK/+; INK4A/Arf−/− and Nestin-Cre; PdgfraJ/+; INK4A/Arf−/− harbored highly proliferative areas in the brain, reflecting early and occasionally more advanced stages of brain tumor growth." (PMID 25683249, 2015). "There were no histological indications of brain tumors in moribund or asymptomatic GFAP:Hi-Otx2 mice aged for up to one year." (PMID 22558385, 2012). "In contrast, markers of differentiated neural cells, such as GFAP (for astrocytes), APC-CC1 (for mature oligodendrocytes), and NeuN (for neurons), were not detectable in brain tumor cells." (PMID 25683249, 2015). "Therefore, this study investigated the potential pretreatment prognostic value of serum neuronal and nonneuronal biomarkers, namely NSE, S100β, GFAP, NGAL, LDH, and lactate, in patients undergoing supratentorial primary brain tumor resection." (PMID 28969023, 2017).
epilepsy (85 papers, 2007 to 2025). A brain disorder characterized by episodes of abnormally increased neuronal discharge resulting in transient episodes of sensory or motor neurological dysfunction, or psychic dysfunction. "It has been reported that elevated levels of GFAP, a marker of astrocytic activation, are often observed in patients with epilepsy and is associated with neuroinflammation, which can possibly impair cognitive functions." (PMID 40291844, 2025). "Further, GFAP expression is also elevated in cases of drug-resistant epilepsy linked to focal cortical dysplasia, highlighting its involvement in neurodegenerative processes." (PMID 40291844, 2025). "We found increased microgliosis (IBA1, P = 0.0087), astrogliosis (GFAP, P = 0.0226) and neuronal loss (NeuN, P = 0.0555), in the cortex of human patients with epilepsy relative to age-matched control brains." (PMID 39355003, 2024). "Well-studied irregularities have been documented in diseases such as Alexander’s, Alzheimer’s, epilepsy, and neuroHIV, in which GFAP is mutated or increased during astrocytosis." (PMID 36818564, 2023). "In line with our results, GFAP positive astrocyte cell loss in the hippocampus has been reported in male rats with epilepsy 4 weeks after SE." (PMID 35449517, 2022). "Epilepsy-associated astrocytosis was evaluated using GFAP immunofluorescence in sections adjected to those employed for NeuN." (PMID 36180719, 2022). "Analysis of GFAP density was carried out at higher magnification in CA1 region as the most susceptible region to GFAP alteration in KA animal models of epilepsy." (PMID 34975386, 2021). "Reactive astrocytes over-expressing GFAP (gliosis) is a hallmark of posttraumatic brain injury and can be see in hippocampal sclerosis, associated with epilepsy." (PMID 29634780, 2018). "Increased levels of certain proteins, such as S100B and glial fibrillary acidic protein (GFAP), in the blood or cerebrospinal fluid, may indicate neuronal damage and could be associated with epilepsy severity." (PMID 41018203, 2025). "In the current study, two patients (5.7%) exhibited focal epilepsy as the only clinical manifestation, showing that GFAP-related autoimmune epilepsy accounted for a specific proportion of children with epilepsy of an unknown cause." (PMID 34880859, 2021). "tested for GFAP antibodies in the blood of 38 children with epilepsy of unknown cause and demonstrated that there were two patients who were seropositive for antiGFAP antibodies." (PMID 34880859, 2021). "In alignment with these findings, our study revealed an elevation in GFAP expression within the medial parabrachial nucleus (MPB) during the chronic phase of epilepsy." (PMID 40170730, 2025). "An unsupervised Ward’s cluster analysis was conducted using the GFAP intermediate variable named “global epilepsy” as well as the whole GFAP." (PMID 41303083, 2025). "They found higher levels of neurofilament light and glial fibrillary acidic protein in drug-resistant epilepsy." (PMID 40114782, 2025). "Like KA-induced epilepsy mouse model, pilocarpine-treated rats exhibited increased GFAP expression in the hippocampal CA1 region, accompanied by a marked decrease in GS expression in GFAP-positive astrocytes." (PMID 41390571, 2025). "We further assessed changes in the expression of FosB and GFAP during the chronic phase of epilepsy through immunofluorescence staining and Western blotting." (PMID 40170730, 2025). "Immunofluorescence staining and Western blotting data on FosB and GFAP expression confirmed the increased excitability of medial parabrachial nucleus neurons and enhanced astrocyte reactivity during the chronic epilepsy phase." (PMID 40170730, 2025). "In younger patients (≤50 years), cases of drug-resistant epilepsy had higher levels of neurofilament light (P = 0.002) and glial fibrillary acidic protein (P = 0.006) compared with monotherapy-controlled epilepsy." (PMID 40114782, 2025).